FUS (FUS RNA binding protein)
Diseases named in the same sentence as FUS in open-access papers (continued):
Sharing a sentence is not in itself a finding about the gene and the disease.
FUS also shares sentences with these, for which no sentence is quoted: multiple system atrophy (7 papers); Parkinsonism (6); synovial sarcoma (4); bone cyst (3); esophageal squamous cell carcinoma (3); fibrosarcoma (3); hereditary spastic paraplegia (3); multiple sclerosis (3); Paget disease of the bone (3); Pick disease (3); adenoid cystic carcinoma (2); Caudate atrophy (2); cognitive disease (2); corticobasal degeneration (2); extraskeletal myxoid chondrosarcoma (2); muscular dystrophy (2); myxoid chondrosarcoma (2); non-small cell lung carcinoma (2); primary progressive aphasia (2); progressive supranuclear palsy (2); psychosis (2); sporadic amyotrophic lateral sclerosis (2); vaginal candidiasis (2); abscess (1); acute basophilic leukemia (1); acute erythroid leukemia (1); acute leukemia (1); acute promyelocytic leukemia (1); Adult onset (1); alveolar rhabdomyosarcoma (1).
A further 84 diseases each share a sentence with FUS in 1 paper.